ID3 (inhibitor of DNA binding 3)
Diseases named in the same sentence as ID3 in open-access papers (continued):
Sharing a sentence is not in itself a finding about the gene and the disease.
cancer (continued). "ID1 and ID3 genes have been identified as predictors of poor response in Colombian adult B-ALL patients, contributing to cancer development." (PMID 39676870, 2024). "We identified several potential CHI3L1 target proteins, including VEGFA, TGF-β1, Cluster of Differentiation 74 (CD74), IL-6, inhibitor of DNA binding 3 (ID3), MMP9, CXCL8, and SPP1, in this type of cancer." (PMID 38177294, 2024). "Recently, we detected that, during the malignization of cancer cells, the opposite effect occurred—the simultaneous extreme upregulation of three ID genes: ID1, ID2, and ID3 (paper in preparation)." (PMID 37372991, 2023). "ChIP-seq analysis revealed that differentially accessible enhancers in aggressive drug-resistant cells had a higher FOXC1 binding, which regulated the expression of adjacent cancer-relevant genes like ABCB1 and ID3." (PMID 35406487, 2022). "To validate our findings, we conducted a study of the literature by randomly selecting five genes (DBF4, MCM2, ID3, EXOSC4, and CDKN3) from the 565 potential cancer genes." (PMID 25866773, 2015). "We investigated whether the expression of ID3 and CD52 was related to cancer features using the UALCAN database." (PMID 39256364, 2024). "First, we selected the down-regulated genes at PNX0010 under PARG overexpression that are related to cancer development: ID1, ID2, ID3, and SERPINE1 and performed qPCR analysis for 786-O, 769-P, SK-RC-45, and SK-RC-26b cell lines treated with the 10 uM PARP-1 inhibitor rucaparib for 24 h." (PMID 34638458, 2021). "Id1/Id3 do have bona fide functional CCAAT in promoters, bound in cancer cells as per ENCODE data (M. Ronzio, A.B., D.D., R.M., in preparation) and in NTera2 cells: Id1, but not Id3, is bound in vivo by NF-Y in C2C12, parental cells and edited clones." (PMID 32214056, 2020). "Overall, in cancer-associated or cancer-adjacent gastric myofibroblasts Dies1 is overexpressed, however the expression of its potential downstream targets, ID2 and ID3, does not follow the same trend." (PMID 27721458, 2016). "In the human network, we also found a significant enrichment for developmental signaling pathways, exemplified by proteins like ID3 and UNC45A, which are involved in cell differentiation and proliferation, and which interact with the cancer drivers MAX and TCF12 respectively." (PMID 26576632, 2015). "This offers new therapeutic options for the treatment of cancers lacking ID3 expression." (PMID 34718742, 2021). "ID1 and ID3 are expressed only in embryonic and cancer cells, but not in most adult tissues." (PMID 34295890, 2021). "Furthermore, while pre-treatment with PC3 conditioned medium reduced myotube size in shCtl cells on day 3, this effect was rescued in cultures lacking ID3, suggesting that the blockade in myogenic differentiation observed in cancer cachexia is mediated through misexpression of ID3." (PMID 30413755, 2018).
infection (9 papers, 2017 to 2024). The state of being infected such as from the introduction of a foreign agent such as serum, vaccine, antigenic substance or organism. "Id3-GFPlo or Id3-GFPhi SMARTA memory CD4+ T cells (28-32 d following primary infection) were transferred into a new cohort of B6 hosts, which were then infected 1 d later with LCMV." (PMID 35858332, 2022). "Consistent with our previous studies, following infection, Id3-GFPhi cells were almost exclusively Tfh (CXCR5hiSLAMlo), while a majority of Id3-GFPlo cells displayed a Th1 phenotype (SLAMhiCXCR5lo)." (PMID 35858332, 2022). "Consistent with our previous observations of high Id3 expression by naive CD8+ T cells, prior to infection more than 95% of CD4+ T cells expressed Id3-GFP." (PMID 35858332, 2022). "Although the Id3 increase seemed rather small, even in infection models, at the peak of the primary response, T-bet expression between terminal effector and precursor memory cells differed only 2-fold, indicating that the differences observed here are sufficient for preferential fate decisions." (PMID 35482418, 2022). "The infection efficiency of Id3 lentiviral vector was validated by fluorescence microscope." (PMID 35599595, 2022). "Id3 reportedly promoted the formation of memory CD8+ T cells upon infection." (PMID 33562631, 2021). "Within this waning population, however, we observed the emergence of an Id3-GFP–expressing memory Th1 population, where ∼15% of Th1 memory cells expressed Id3-GFP by day 41 following infection." (PMID 35858332, 2022). "While the frequency of Id3-GFP–expressing Th1 cells increased as the total Th1 population contracted, the absolute number of Id3-GFP–expressing Th1 cells was evident as early as day 7 of infection and was mainted into the memory timepoint." (PMID 35858332, 2022). "We show that expression of Id3 definitively identified a subset of cells within both the CD4+ Tfh and T helper 1 (Th1) lineages at memory time points that exhibited memory potential, with the capacity for significant re-expansion in response to secondary infection." (PMID 35858332, 2022).
kidney disease (2 papers, 2017 to 2023). "Apolipoprotein E deficiency is known to cause enlarged immune responsiveness and these results add significance to the study in dissecting the effects of ID3 alone on kidney disease." (PMID 28785583, 2017).
Metabolic Disorders (2 papers, 2017 to 2018). "This may lead to novel pathways for how the interaction of ID3, EDCs, and metabolic disorders exacerbates complex chronic disease and can help public health professionals control these metabolic disorders." (PMID 28785583, 2017).
ID3 also shares sentences with these, for which no sentence is quoted: cholangiocarcinoma (3 papers); diabetes (3); papillary thyroid cancer (2); adrenal carcinoma (1); adrenal cortical carcinoma (1); Alzheimer disease (1); Anxiety (1); B-cell acute lymphoblastic leukaemia (1); B-cell acute lymphoblastic leukemia (1); bacterial infections (1); brain cancer (1); brain injury (1); brain tumors (1); breast invasive carcinoma (1); cardiac disease (1); cerebrovascular disease (1); Chronic colitis (1); chronic myeloid leukemia (1); colorectal (1); colorectal adenocarcinoma (1); diffuse intrinsic pontine glioma (1); diffuse large B-cell lymphoma (1); endometrial carcinoma (1); Ewing sarcoma (1); follicular lymphoma (1); glomerulonephritis (1); Glucose intolerance (1); Hearing Loss (1); Hepatic steatosis (1); hereditary hemorrhagic telangiectasia (1).
A further 23 diseases each share a sentence with ID3 in 1 paper.